SPOCK1 (SPARC (osteonectin), cwcv and kazal like domains proteoglycan 1)
Diseases named in the same sentence as SPOCK1 in open-access papers (continued):
Sharing a sentence is not in itself a finding about the gene and the disease.
tumor (continued). "Moreover, IHC staining showed less Ki-67 positive cells in SPOCK1-depleted inoculated tumor tissues." (PMID 25623055, 2015). "Moreover, gene set enrichment analysis (GSEA) revealed that the high SPOCK1 expression group was also enriched in inflammation and hypoxia-related pathways, supporting its role in shaping a pro-metastatic and immunosuppressive tumor microenvironment (TME)." (PMID 40837013, 2025). "Lastly, bioinformatic and immunohistochemical analysis determined that elevated SPOCK1 gene levels correlate with increased immune-suppressive macrophage infiltration and decreased CD8+ T-cell presence in high-risk BCs, suggesting a role in the immune remodelling of the tumour niche." (PMID 41463344, 2025). "Similarly, it was reported that miR-940 could reversely regulate CKS1, MACC1, MTHFD2 and SPOCK1 in tumors, indicating its significant function in tumor occurrence and development." (PMID 35297315, 2022). "Indeed, a recent investigation revealed that SPOCK1-promoted tumor growth and metastasis are accompanied by upregulation of MMP-3 and MMP-9 expressions in PCa, suggesting that MMPs may be involved in the SPOCK1-mediated EMT process and subsequent metastasis." (PMID 31182131, 2019). "Interestingly, these data are consistent with the predictive potential of EPCR levels in these three subsets, but not in luminal A. This finding suggests that EPCR could mediate tumor progression in part by upregulating SPOCK1." (PMID 28103946, 2017). "Therefore, EPCR could promote tumor growth in vivo, in part, by modulating tumor-matrix interactions through SPOCK1 favoring an advantageous 3D growth of tumorigenic cells." (PMID 28103946, 2017). "The expression of SPOCK1 was significantly positively correlated with ANXA2, implying a potential synergistic role in promoting tumor metastasis." (PMID 40837013, 2025). "Multiplex immunohistochemistry (mIHC) further confirmed their spatial co-localization within tumor regions, indicating potential cell–cell communication between CAF+SPOCK1 and malignant epithelial cells." (PMID 40837013, 2025). "In our study, when SPOCK1 expression levels were compared in normal and cancerous tissue samples, it was found to be significantly lower, especially in CESC and UCEC tumor tissues (p < 0.05)." (PMID 40001977, 2025). "Given the high SPOCK1 expression in CAFs, and its elevated levels in tumor versus normal tissues, CAFs were stratified into SPOCK1-high (CAF+SPOCK1) and SPOCK1-low (CAF−SPOCK1) groups." (PMID 40837013, 2025). "Studies have indicated that SPOCK1 can promote the abnormal activation of MMP-3, MMP-9, and MMP-2, leading to directed migration of tumor cells from the edge of the tumor mass and ultimately inducing ECM remodeling." (PMID 38087364, 2023). "Meanwhile, SPOCK1 and POSTN were enriched in a variety of immune-related pathways and were related to the regulation of tumor immune cells and the expression of multiple immune checkpoint genes." (PMID 36611136, 2023). "Previous studies have mentioned that the SPOCK1-mediated EMT and tumor progression via activation of the PI3K/Akt signaling pathway in various cancer types." (PMID 36766694, 2023). "The overexpression of SPOCK1 can lead to poor survival outcomes by driving EMT and inducing immune escape of tumor cells." (PMID 38087364, 2023). "In spite of these reports, SPOCK1 is still considered as an ECM proteoglycan, and interestingly hardly any account paid attention that it can be detected in tumor cells of surgically removed human cancer tissues, and also in the cytoplasm of cancer cell lines." (PMID 35186754, 2022). "Knockdown of miR-135b decreased the expression level of SPOCK1, glucose consumption and lactic secretion in CRC patient-derived tumours organoids (CRC tPDOs)." (PMID 35046388, 2022). "Some new tumor-specific markers for different pathologic types of RCC, such as SPOCK1, PTGIS, REG1A, CP and SPAG4 were identified and validated." (PMID 34722263, 2021).
tumor (continued). "In summary, our work was focused on the methylation and expression analyses of GRIA4, VIPR2, SPOCK1 and SLC6A3, belonging to gene families involved in the crosstalk between tumour cells and the environment." (PMID 32599859, 2020). "SPOCK1, SLC6A3 and GluR4 were significantly low-expressed in tumour respect to normal tissues, following the same pattern of the mRNA expression level." (PMID 32599859, 2020). "Our data imply that SPOCK1 expression mediates EMT signaling activation in vitro, thus, we further detected SPOCK1 and EMT biomarkers by Western blotting in mice bearing tumor xenografts." (PMID 31182131, 2019). "SPOCK1 is a glycoprotein, highly similar to SPARC, a well‐studied and characterized protein in the context of PDAC tumor growth." (PMID 28486750, 2017). "Recently, the significance of SPOCK1 for tumor growth, apoptosis, epithelial‐to‐mesenchymal transition (EMT), and metastasis has been reported for tumor types other than PDAC." (PMID 28486750, 2017). "Unexpectedly, EPCR modulates tumor cell-ECM interactions involved in 3D growth required for tumor progression and metastasis, in part by upregulating SPOCK1." (PMID 28103946, 2017). "To functionally establish the relative potency of TGF‐β to induce SPOCK1 compared to other ligands known to mediate tumor–stroma crosstalk in PDAC, we applied a panel of such ligands to the PS‐1 cells and determined SPOCK1 levels by qRT‐PCR." (PMID 28486750, 2017). "By integrating bulk RNA sequencing, single-cell transcriptomics, and spatial transcriptomics data, we found that SPOCK1 is generally overexpressed in tumor tissues compared to normal tissues." (PMID 40837013, 2025). "Moreover, high SPOCK1 expression was associated with lower tumor mutational burden (TMB) and homologous recombination deficiency (HRD) scores, indicating that SPOCK1 may influence DNA repair capacity and tumor heterogeneity, ultimately contributing to treatment resistance and metastatic potential." (PMID 40837013, 2025). "Targeting SPOCK1 itself or its downstream signaling axes may disrupt CAF functionality, reduce metastatic potential, and reprogram the tumor immune microenvironment." (PMID 40837013, 2025). "Our cell communication analysis suggests that SPOCK1+ CAFs may regulate ANXA2 expression through an autocrine mechanism involving insulin-like growth factor (IGF) signaling, thereby influencing tumor progression." (PMID 40837013, 2025). "However, it has been found that SPOCK1 is predominantly expressed in the stromal compartment of tumors, aiding in ECM remodeling, which is essential for tumor cell invasion." (PMID 39595089, 2024). "In tumors that had not been treated with chemotherapy, where SPOCK1 exerted strong staining, tumor cell nuclei were also positive for CHD1L." (PMID 37046698, 2023). "These suggested that high expression of SPOCK1 and POSTN might be correlated with tumor immune evasion in CRC." (PMID 36611136, 2023). "In summary, SPOCK1 can promote LUAD invasion and metastasis through various mechanisms, and this may also be one of the reasons for tumor evasion of immune surveillance." (PMID 38087364, 2023). "Although examining the signaling network affected by SPOCK1 transfection was not the purpose of our study, we did see alterations in the level of a crucial tumor suppressor, p21CIP1." (PMID 37046698, 2023). "In addition to the EMT, SPOCK1 was reported to be an ECM proteoglycan, which directly or indirectly regulates ECM remodeling, thus affecting tumor progression." (PMID 36766694, 2023). "In our study, the KD gene SPOCK1 was regulated by miR-155-5p, which can form a regulatory feedback loop with STAT1 and might trigger cancer immunoediting to allow tumour cells to escape immunosurveillance and even to promote tumourigenesis." (PMID 33902514, 2021).
tumor (continued). "To explore whether SPOCK1 is an effective therapeutic target of API in PCa, we tested the role of SPOCK1 in tumor metastasis and the antimetastatic activity of API in vivo using stable SPOCK1-silenced PC-3 M-Luc cells or SPOCK1-overexpressing PC-3-Luc cells." (PMID 31182131, 2019). "Tumour tissues exhibited significantly higher level of SPOCK1 protein than that in noncancerous gastric tissues." (PMID 28940639, 2018). "Our previous analyses did not exclude the possibility that SPOCK1 is also expressed in the tumor cells in PDAC." (PMID 28486750, 2017). "We show that its expression is driven by tumor cell‐derived transforming growth factor‐beta (TGF‐β) and that the function of SPOCK1 is to translate the reception of this ligand into stromal support for tumor cell growth and migration via the modulation of the extracellular collagen matrix." (PMID 28486750, 2017). "Furthermore, we showed that EPCR effects in tumor progression were APC independent and were partially mediated by a novel mechanism involving SPOCK1." (PMID 28103946, 2017). "In the shSpock1 cocultures, this population was notably absent, which implies that stromal SPOCK1 also enables invasive growth of tumor cells." (PMID 28486750, 2017). "To more conclusively address the impact of stromal SPOCK1 on tumor cell growth patterns, and for lack of a feasible in vivo model to study this, we turned to advanced organotypic culturing models." (PMID 28486750, 2017). "We demonstrated that stromal SPOCK1 does not directly affect the chemoresistance of tumor cells, but that stromal SPOCK1 does strongly contribute to tumor growth and invasiveness in three‐dimensional cultures." (PMID 28486750, 2017). "In the absence of SPOCK1, tumor cells are more mechanically restricted by the matrix, possibly explaining the prognostic value of SPOCK1 in PDAC." (PMID 28486750, 2017). "The relative expression level of SPOCK1 was significantly higher in tumor tissues compared with that in their nontumor counterparts (P = 0.016)." (PMID 25623055, 2015). "Furthermore, to assess the effects of SPOCK1 on GBC growth in vivo, SPOCK1-depleted or control NOZ cells were injected into the left axilla of nude mice, and then the tumor volume was monitored." (PMID 25623055, 2015). "To explore the role of SPOCK1 in the progression of GBC, we detected the endogenous expression of SPOCK1 in tumor and nontumor tissues, and five GBC cell lines by RT-PCR and western blotting." (PMID 25623055, 2015). "Thus, we hypothesize that CAF+SPOCK1 cells may upregulate ANXA2 expression and phosphorylation through autocrine IGF signaling, further promoting EMT and tumor progression." (PMID 40837013, 2025). "The combined data indicate that SPOCK1 in BC is not simply indicative of a tumour-intrinsic change and may be involved in a stromal–ECM–immune interaction." (PMID 41463344, 2025). "On the other hand, chemotherapy-treated tumor samples with weak SPOCK1 expression were negative for CHD1L, suggesting that the regulatory mechanism of SPOCK1 may appear at mRNA level." (PMID 37046698, 2023). "To confirm the role of SPOCK1 in anti-tumorigenesis activity of API by IHC staining, we found that SPOCK1 staining was markedly decreased in shSPOCK1 and API treatment, whereas SPOCK1-overexpressing tumor tissues were strongly stained, and the suppressive effects of API had been restored." (PMID 31182131, 2019). "Similarly, to ascertain whether SPOCK1 could exert an influence on tumour formation in vivo, SGC7901 cells (sh‐NC and sh‐SPOCK1) or AGS cells (Vector and SPOCK1) were inoculated subcutaneously into nude mice develop implant tumour, respectively." (PMID 28940639, 2018). "SPOCK1 was significantly upregulated in tumor tissue compared to nontumor samples." (PMID 28486750, 2017).
tumor (continued). "Considering the complexity of PDAC architecture, the true “invasive front” of a tumor cannot be reliably identified in a 2-dimensional tissue section, so we could not determine whether SPOCK1 or OLR1 expression was enhanced in the most invasive PDAC cells in vivo." (PMID 36881486, 2023). "The SPOCK1 gene was not significantly different in OV tissues (p > 0.05), but it was lower in CESC and UCEC tumor tissues than in normal tissues (p < 0.05)." (PMID 40001977, 2025). "According to fold changes of expression level between non-tumor and tumor, representative target genes were CLIP2, TREM1 (miR-26a), SPOCK1 (miR-375), PENK, and ADAMTS16 (miR-1260)." (PMID 32313120, 2020).
cancer (52 papers, 2010 to 2026). A tumor composed of atypical neoplastic, often pleomorphic cells that invade other tissues. "SPOCK1 is a gene associated with cancer growth and poor survival rates in various cancers, although its significance in gynecological tumors is not fully understood." (PMID 40001977, 2025). "SPOCK1 was found to be linked to age, cancer stage, weight, and menopausal status in particular cancer types." (PMID 40001977, 2025). "SPOCK1 was broadly overexpressed in multiple cancer types and significantly associated with poor prognosis in BRCA." (PMID 40837013, 2025). "Along with controlling the ECM’s dynamic balance, SPOCK1 also controls cellular characteristics linked to cancer, including invasion, metastasis, and apoptosis." (PMID 40001977, 2025). "The enrichment of SPOCK1 in cancer-associated fibroblasts (CAFs) and its prominent interactions with malignant epithelial cells underscore its potential as a therapeutic target." (PMID 40837013, 2025). "Alone or as part of gene signatures, SPOCK1 has been associated with poor survival in various cancer types." (PMID 37046698, 2023). "The SPOCK1 gene has ten splice variants, of which three isoforms are predominantly expressed in all cancers." (PMID 37046698, 2023). "High tumoral SPOCK1 expression has been associated with increased growth, invasiveness and metastasis in many cancer types." (PMID 35221802, 2022). "For example, Tff3, Hpse, Slit1, Spon1, Spock1, and Spock3 are associated with increased cancer cell invasion and were upregulated in Rreb1-/-, and Selenbp1 and Serpin6b are tumor suppressor genes that were downregulated." (PMID 33929320, 2021). "The region on BTA 7 overlaps with a previously reported region for Mycobacterium paratuberculosis susceptibility in U.S. Holsteins and encompasses the SPOCK1 gene, which has been shown to be associated with cancer in humans." (PMID 32582285, 2020). "Nevertheless, the underlying mechanisms and functions of SPOCK1-induced BC activities, including cancer development and metastasis processes, are far from clear." (PMID 33293473, 2020). "SPOCK1, also known as testican-1, is a proteoglycan that belongs to a Ca2+-binding proteoglycan family that was implicated in cell proliferation, DNA replication, apoptosis, and the migration and invasion of cancer cells." (PMID 31182131, 2019). "Single-sample gene set enrichment analysis (ssGSEA) indicated that SPOCK1 expression positively correlated with immune scores in some cancer types but negatively correlated in others." (PMID 40837013, 2025). "Our pan-cancer analysis revealed that SPOCK1 expression positively correlates with multiple immune-related genes, including chemokines, immunosuppressive molecules, and major histocompatibility complex (MHC) components." (PMID 40837013, 2025). "SPOCK1 has been reported in various cancers, where it is involved in promoting cell proliferation, angiogenesis, and EMT." (PMID 40837013, 2025). "SPOCK1 mRNA levels are increased in some cancers, including lung, liver, esophageal, stomach, colorectal, breast, prostate, and head and neck cancers." (PMID 40001977, 2025). "Our results showed that SPOCK1 expression is significantly positively correlated with these immune genes in most cancer types." (PMID 40837013, 2025). "Immune-related gene sets, including chemokines, immunoinhibitors, major histocompatibility complex (MHC), and receptors, were retrieved from the TISIDB database, and their correlation with SPOCK1 was analyzed across cancers." (PMID 40837013, 2025). "After being identified, previous studies reported that SPOCK1 functions as a metastasis-related gene in several cancers, which promotes the EMT of cancer cells, resulting in distant cancer metastasis." (PMID 36766694, 2023). "The analysis showed that SPOCK1 was negatively correlated with CD8+ T cell infiltration in most cancers." (PMID 38087364, 2023).